HP (haptoglobin)
Diseases named in the same sentence as HP in open-access papers (continued):
Sharing a sentence is not in itself a finding about the gene and the disease.
atherosclerosis (14 papers, 2009 to 2025). A disease characterized by the build-up of fatty material and calcium deposition in the arterial wall resulting in partial or complete occlusion of the arterial lumen. "The haptoglobin polymorphism is related to the prevalence and clinical evolution of many inflammatory diseases, including atherosclerosis." (PMID 36358920, 2022). "Despite the presence of three HP genotypes: HP1-1, HP2-1, and HP2-2, all of which are associated with susceptible infectious diseases, atherosclerosis, autoimmune disorders, and vascular occlusive diseases." (PMID 35860021, 2022). "We suggest that future researches of HP strains in large prospective trials and intervention studies are required to ascertain the possible function of HP in atherosclerosis." (PMID 30242291, 2018). "It is also a potential serum marker for atherosclerosis disease progression besides its role in the clearance of hemoglobin in the form of haptoglobin-hemoglobin complex by the third scavenger receptor cysteine-rich (SRCR) domain of CD163." (PMID 27563889, 2016). "This work will further contribute to our understanding of the role of haptoglobin on modulating reverse cholesterol transport as well as the development of atherosclerosis." (PMID 19627602, 2009). "And the haptoglobin polymorphism could contribute to the prevalence and clinical evolution of many inflammatory diseases, including T2DM and atherosclerosis." (PMID 29633887, 2018). "Their plasma revealed downregulation of certain cardiovascular-protective proteins such as apolipoprotein A-IV, haptoglobin, and hemopexin, which could explain the accelerated atherosclerosis process accompanying HD." (PMID 22792249, 2012). "Haptoglobin, HDL and PLTP activity correlation data suggests the potential to use haptoglobin as a biomarker for the development of atherosclerosis as well as a tool to understand the role of PLTP activity and haptoglobin levels in reverse cholesterol and atherosclerosis." (PMID 19627602, 2009). "In our study, postprandial plasma CRP, but not haptoglobin, IL-6 or TNF-α, positively correlated with the severity of beginning atherosclerosis." (PMID 21756316, 2011).
metabolic syndrome (14 papers, 2011 to 2023). A cluster of metabolic risk factors for CARDIOVASCULAR DISEASES and TYPE 2 DIABETES MELLITUS. "The association between copper availability, iron metabolism, haptoglobin polymorphism, and metabolic syndrome requires clarification." (PMID 21190397, 2011). "They showed that individuals with metabolic syndrome had elevated Hb, ferritin, erythropoietin, and haptoglobin concentrations." (PMID 36361221, 2022). "Increased haptoglobin levels were found in subjects with elevated blood pressure, elevated glucose levels, or metabolic syndrome." (PMID 28282855, 2017). "Subjects with metabolic syndrome, here defined by low water T2, displayed statistically significant increases in the mean concentrations of fibrinogen, complement C3c, haptoglobin, apolipoprotein B, α1-acid glycoprotein and complement C4c, as well as total plasma proteins and globulins (black bars)." (PMID 29258604, 2017). "Zonulin could possibly be used clinically as a marker of the metabolic syndrome in the same way for the mature haptoglobin molecule." (PMID 28282855, 2017). "For example, C-reactive protein and haptoglobin, which both increased with age in the ASD subjects, are components of the acute phase response, although these same proteins have also been used as biomarkers for immune disorders and metabolic syndrome." (PMID 23915542, 2013). "While previous reports have shown elevation in haptoglobin (HPT) in individuals with elevated glucose and metabolic syndrome, alterations in ANK-1 do not appear to have been reported previously." (PMID 36902363, 2023).
sickle cell disease (14 papers, 2012 to 2026). Sickle cell anemias are chronic hemolytic diseases that may induce three types of acute accidents: severe anemia, severe bacterial infections, and ischemic vasoocclusive accidents (VOA) caused by sickle-shaped red blood cells obstructing small blood vessels and capillaries. "The results indicate a significant association between HP gene polymorphisms and sickle cell disease severity under the dominant model (odds ratio = 0.76; 95% confidence interval: 0.61-0.94; p-value = 0.01)." (PMID 42140015, 2026). "This review outlines the current clinical research investigating how the haptoglobin (Hp) genetic polymorphism and stroke occurrence are implicated in sickle cell disease (SCD) pathophysiology." (PMID 35052484, 2022). "The purpose of this study was to describe the relationships among iron, oxidative stress, and the genetic polymorphism of haptoglobin in sickle cell anemia patients with inflammation, and to explore how these factors are associated with the pathophysiology of the disease." (PMID 41473578, 2025). "This study hypothesizes that the HP2 allele of haptoglobin may exacerbate oxidative stress in patients with sickle cell anemia with inflammation." (PMID 41473578, 2025). "Observations made from this study suggest that haptoglobin is a major contributor to the worsening pathophysiology of sickle cell anemia; however, a study of a larger size would allow for more conclusive results." (PMID 41473578, 2025). "To further address the mechanism, we used a hyperhemolytic murine model (Townes-SS) of sickle cell disease to examine cellular responses to haptoglobin and hemopexin supplementation." (PMID 29694434, 2018). "It should be noted that markers such as Haptoglobin, included in both Fibrotest and Actitest, are strongly expressed in subjects infected by chronic malaria and sickle cell anaemia, two prevalent conditions in Bamako." (PMID 25886382, 2015).
thrombotic microangiopathy (14 papers, 2009 to 2026). The syndromes of microangiopathic hemolytic anemia, thrombocytopenia, and variable signs of organ impairment, due to platelet aggregation in the microcirculation. "One month later the patient was readmitted in our unit owing to the recurrence of peripheral thrombotic microangiopathy (platelets: 130000/mm3, Hemoglobin: haptoglobin < 0.01 g/dl, schistocytes: 1%, LDH: 740 UI/L) and AKI with a creatinine level of 470 μmol/L." (PMID 32652955, 2020). "Severe life-threatening haematologic findings such as pancytopaenia, thrombotic microangiopathy and haemolytic anaemia (high LDH, low haptoglobin, schistocytes and thrombopaenia) due to cobalamin deficiency were observed in our patient." (PMID 19946556, 2009). "However, the patient had mildly elevated LDH and bilirubin, decreased haptoglobin, reduced fibrinogen, and elevated D-dimer with mild coagulopathy, raising the possibility of DIC or cancer-associated thrombotic microangiopathy." (PMID 41536396, 2025). "Although the ADAMTS13 test was not performed for technical reasons, considering hemolysis parameters, haptoglobin, LDH, and bilirubin were within the reference range, and the suspicion of thrombotic microangiopathy (TMA) was excluded." (PMID 39860022, 2025).
microangiopathic hemolytic anemia (13 papers, 2012 to 2025). "If the LDH level is elevated, other tests should be used to confirm microangiopathic hemolytic anemia, including peripheral blood smear, haptoglobin, and/or direct Coombs tests." (PMID 38396391, 2024). "Peripheral blood smear, haptoglobin and hemoglobin level confirmed microangiopathic hemolytic anemia." (PMID 32481360, 2020). "Given the fact that all patients demonstrated microangiopathic hemolytic anemia [elevated lactose dehydrogenase (LDH), reduced haptoglobin levels, and/or fragmentocytes), the concept of endothelial cell damage appears to be a central pathogenic factor." (PMID 27289364, 2017).
coronary artery disease (12 papers, 2013 to 2025). "In the ACCORD study, participants with the haptoglobin (Hp) 2–2 phenotype and glycated hemoglobin (HbA1c) ≥ 8.0% had a higher risk of coronary artery disease (CAD) compared to those with HbA1c 7.0–7.9%." (PMID 39385258, 2024). "Logistic regression analysis showed that a decrease in haptoglobin expression correlates with an increased risk of coronary heart disease." (PMID 36361589, 2022). "However, hypertensive patients with the allele T rs217181, and with a higher level of haptoglobin, had more severe coronary heart disease in the Chinese population." (PMID 36361589, 2022). "In the early stages of this research field, especially before 2000, scholars mainly focused on inflammation (#0), coronary artery disease (#6), haptoglobin (#8), and heart failure (#10)." (PMID 39791171, 2025). "A common variation in the gene that codes for the abundant plasma protein haptoglobin (Hp) identifies individuals who may be at increased risk of coronary artery disease (CAD, such as myocardial infarction) from hyperglycemia." (PMID 38402400, 2024). "Serum HP, an acute-phase protein synthesized primarily from hepatocytes, is known to be involved in coronary artery diseases and Kawasaki disease." (PMID 33344384, 2020). "In this study, we investigated whether the HP genetic variant, rs217181, is associated with coronary artery disease (CAD) severity and cardiovascular mortality (excluding stroke) in two Singapore Chinese populations." (PMID 32794371, 2020). "Comparison of participants’ characteristics by coronary artery disease status and haptoglobin concentration (low or high)." (PMID 24130793, 2013). "The level of haptoglobin significantly reduced in patients with stable coronary artery disease (CHD) and acute coronary syndrome (ACS) compared with healthy controls." (PMID 36361589, 2022).
endometritis (12 papers, 2013 to 2025). An acute or chronic, usually bacterial infectious process affecting the endometrium. "Longer-term consequences associated with elevated HP in circulation, metritis, endometritis, or PVD include delayed resumption of ovulation and decreased estrus detection and reproductive performance." (PMID 40075916, 2025). "Some studies have confirmed the association between the serum concentration of haptoglobin and the uterine infection postpartum." (PMID 36144832, 2022). "In addition to hypocalcemia and elevated NEFA and BHB, elevated concentrations of the acute phase protein (APP) haptoglobin (HP) in circulation have been associated with an increased risk of metritis, endometritis, or purulent vaginal discharge (PVD)." (PMID 40075916, 2025). "Furthermore, studies suggested that SAA and HP could be used to monitor and predict treatment response in uterine tract infections and endometritis and that lameness associated with F. necrophorum infections causes higher HP and SAA responses than non-F." (PMID 39237955, 2024). "Previous studies indicated elevated levels of haptoglobin as early as 5-day post-partum in cows developing subclinical endometritis in later stages post-calving." (PMID 36172606, 2022). "In the first study, the effects of a mixture of lactic acid bacteria on the incidence of purulent vaginal discharge/clinical endometritis, plasma haptoglobin concentrations, and milk production in dairy cows were investigated." (PMID 33029222, 2020). "Intravaginal administration of the cocktail decreased the incidence of clinical endometritis at three weeks postpartum and reduced acute phase protein haptoglobin in weeks two and three postpartum." (PMID 33029222, 2020). "The divergence in APPs, particularly in HP expression levels between cows with uterine infection and cows that are healthy postpartum has been previously reported." (PMID 26482908, 2015). "In an observational study, we recently evaluated the spontaneous P4 profiles from 35 to 70 DIM in postpartum cows that had indications of both systemic inflammation in the first week postpartum (serum HP ≥ 0.8 g/L) and endometritis (≥6% endometrial PMN) at 35 DIM compared to healthy cows." (PMID 40075916, 2025). "Cows with elevated blood HP or metritis are at greater risk of chronic uterine diseases such as PVD and endometritis (defined as ≥6% polymorphonuclear cells in endometrial cytology), which affect approximately 15% and 20% of cows in the second month of lactation, respectively." (PMID 40075916, 2025). "Additionally, using a cut-off of 0.085 mg/mL for HP gave a sensitivity and specificity of 95% and 57.5%, respectively, between healthy cows and those with moderate endometritis." (PMID 39237955, 2024). "Several studies have also identified metabolites such as non-esterified fatty acid, beta-hydroxybutyrate, and haptoglobin in the blood of cows with endometritis, which have the ability to predict and diagnose endometritis." (PMID 38998045, 2024). "In this report, subclinical endometritis had lower serum total calcium (tCa) at 7 d before calving, and greater serum non-esterified fatty acid (NEFA), β-hydroxybutyrate (BHB), globulin (GLB), and haptoglobin (Hp) in the early postpartum period." (PMID 36496919, 2022). "Measurement of serum amyloid A and haptoglobin was not proven useful for diagnosis of subclinical endometritis in Icelandic mares." (PMID 27604098, 2016).
haemolytic anaemia (12 papers, 2009 to 2025). "The release of free haemoglobin into the vascular system following a haemolytic crisis or the onset of haemolytic anaemia will therefore cause a marked loss of haptoglobin." (PMID 24885808, 2014). "Additional laboratory investigations revealed reduced haptoglobin (< 1 mg/dl), high reticulocyte count (9.34%) and positive Coombs test, all suggestive of haemolytic anaemia." (PMID 31118063, 2019). "Targeting haptoglobin could offer therapeutic benefits in conditions characterised by excessive haemolysis, such as sickle cell disease, haemolytic anaemias, and autoimmune haemolytic conditions." (PMID 40606553, 2025). "Additionally, it often shows biochemical signs of haemolytic anaemia, such as increased indirect bilirubin and decreased serum haptoglobin." (PMID 39640193, 2024). "The initial drop in haptoglobin at the pre-metastatic phase could indicate haemolytic anaemia and most probably also be due to oxidative stress handling." (PMID 31042781, 2019).
psoriasis (11 papers, 2012 to 2025). An autoimmune condition characterized by red, well-delineated plaques with silvery scales that are usually on the extensor surfaces and scalp. "Recently, It was reported that increased glycan branches and fucose content of haptoglobin (Hp) were associated with psoriasis." (PMID 33507566, 2021). "To complement the data from the RT-qPCR analysis and to elucidate the underlying molecular mechanisms of action of HP, VER and LEU we further examined the protein abundance of key transcription factors, involved in psoriasis pathogenesis." (PMID 34834106, 2021). "Analogously, increased salivary levels of haptoglobin were found, suggesting a local mechanism against psoriasis." (PMID 34209865, 2021). "Plasma in psoriasis patients has been shown to have reduced activity of haptoglobin, an acute phase glycoprotein, and an LCAT inhibitor." (PMID 32916896, 2020). "In the urine of psoriasis patients with a high cumulative MTX dose, some proteins that are known to be associated with hepatic fibrosis were identified, including haptoglobin, N-cadherin, serotransferrin, and inter-alpha-trypsin inhibitor heavy chain H4." (PMID 26362816, 2015). "Haptoglobin (Hpt), a glycoprotein secreted by hepatocytes and other types of cells including keratinocytes, was found with glycan changes in psoriasis and other diseases." (PMID 23272204, 2012). "Furthermore, increased salivary haptoglobin levels were also documented, indicating a potential local defense response in the context of psoriasis." (PMID 40731810, 2025). "97% of the patients with psoriasis also had higher levels of haptoglobin than the controls." (PMID 29619128, 2018). "Similarly, increased salivary levels of Haptoglobin were reported, indicating a local defense mechanism against psoriasis." (PMID 29888276, 2018). "Patients with skin diseases, e.g., psoriasis, had a significantly increased haptoglobin mRNA expression in epidermal keratinocytes compared to controls, and it was suggested that keratinocyte-derived haptoglobin may contribute to the downregulation of inflammatory responses in the skin." (PMID 32556497, 2020). "In many studies, different salivary components have been evaluated in psoriasis patients, such as salivary total protein, salivary immunoglobulin A (IgA), IgG, lysozyme, C-reactive protein (CRP), and Haptoglobin." (PMID 29888276, 2018). "Haptoglobin‐synthesizing keratinocytes might play a role of negative feedback regulation in the pathogenesis of psoriasis." (PMID 33507566, 2021).
rheumatoid arthritis (11 papers, 2014 to 2025). A chronic, systemic autoimmune disorder characterized by inflammation in the synovial membranes and articular surfaces. "Altered glycosylation patterns in plasma AGP and haptoglobin have been found to be associated with the pathogenesis of rheumatoid arthritis." (PMID 24346772, 2014). "We aimed to assess hepatic proteins in rheumatoid arthritis patient’s: inflammation markers (high-sensitive C-reactive protein (CRPhs), haptoglobin (Hp)), and those implicated in iron metabolism (ferritin, Albumin (Alb), Cp, α-1-acid glycoprotein (AAG) and Tf) and MPO." (PMID 28894708, 2017). "Anti-TNFa therapy in patients with rheumatoid arthritis decreased cytokines and acute phase proteins including IL-6, IL-1 receptor antagonist, serum amyloid A, haptoglobin, and fibrinogen." (PMID 35740360, 2022). "Ficolin 3, Haptoglobin, Alpha-1-antitrypsin, Hemopexin precursor and IgM chain also showed increased expression in plasma of rheumatoid arthritis patients as an indication of immune response." (PMID 25350754, 2014). "In addition, when studying the genetic subtypes of haptoglobin in the synovial fluid in patients with rheumatoid arthritis, no obvious correlation was found with elevated levels in all three haptoglobin types studied." (PMID 35964131, 2022).
Stroke (11 papers, 2010 to 2025). Sudden impairment of blood flow to a part of the brain due to occlusion or rupture of an artery to the brain. "As for the diagnostic power of the atherothrombotic stroke, only a few have real potential, such as haptoglobin and serum amyloid A. Both showed high specificity and sensitivity for diagnostic." (PMID 34445740, 2021). "Haptoglobin levels in rat brain increase with aging and haptoglobin polymorphisms or phenotypes have been associated with differences in the incidence and severity of vascular diseases, including stroke." (PMID 28966798, 2017). "To evaluate whether the observed association between CSF haptoglobin and outcomes after aSAH reflected a broader cerebrovascular effect, we examined a range of related phenotypes, including stroke subtypes, white matter hyperintensities, cerebral microbleeds, and perivascular space burden." (PMID 40763130, 2025). "Conversely, elevation in MIF (OR: 0.8078, 95% CI: 0.6748-0.9670, PIVW: 0.0200) and haptoglobin (OR: 0.9034, 95% CI: 0.8234-0.9911, PIVW: 0.0317) was associated with a decreased risk of stroke." (PMID 39253091, 2024). "Evaluated carboxyhemoglobin levels are associated with increased levels of inflammation‐sensitive proteins, such as fibrinogen, haptoglobin, and ceruloplasmin, all of which have established links with cardiovascular disease and stroke." (PMID 38376055, 2024). "Considering few studies focusing on the intermediate role of haptoglobin between depression and stroke, this study provides new insight and reference for investigating its potential roles in the comorbidity, such as PSD." (PMID 37065487, 2023). "In conclusion, our study is the first to investigate the association and interaction effect of HP genetic variants and common CAD risk factors on CAD severity and cardiovascular mortality (excluding stroke) in the East‐Asian Chinese population." (PMID 32794371, 2020).